TNF (tumor necrosis factor)
Diseases named in the same sentence as TNF in open-access papers (continued):
Sharing a sentence is not in itself a finding about the gene and the disease.
tumor (continued). "TNF-α is a cytokine with a great role in tumor immune surveillance that has a significant contribution to the progression of cancer." (PMID 34395492, 2021). "Accordingly, we detected strong expression of IL-1β and other inflammatory cytokines such as tumor necrosis factor (TNF) in SCC VII and 4T1 tumors (which include macrophages) grown in mice, but barely in the underlying tumor cells." (PMID 34876407, 2021). "Similar to the double-edged sword of IFN-γ, TNF-α has shown a dual tumor suppressing and tumor promoting role dependent on concentration and localization of the soluble cytokine." (PMID 34012451, 2021). "Th17-like Tregs that expressed IL-17, IL-22, IL-2, TNF and RORγt but in parallel maintained Foxp3 expression markedly enhanced anti-tumor immunity." (PMID 34539668, 2021). "NF-κB mediates a crosstalk between inflammation and the accumulation of proinflammatory cytokines cytokines such as TNF-alpha, and IL-6 in a tumor microenvironment with elevated NF-κB activity leads to the protumorigenic microenvironment." (PMID 34394838, 2021). "ICIs also release T cells, with subsequent production of pro-inflammatory cytokines such as IFN-γ and TNF, resulting in excessive autoimmunity tumor inflammation." (PMID 34071550, 2021). "Proinflammatory S100A8 and S100A9, whose expression is induced by factors secreted from primary tumours such as TNF-α, TGF-β and VEGF-A, serve as recruiters of CD11b+ myeloid cells into the pre-metastatic lungs, in turn promoting metastasis formation." (PMID 35006432, 2021). "Considering its over expression, TNF-α was identified as a key pro-inflammatory cytokine which stimulate tumor progression at day 93 PI." (PMID 34946170, 2021). "M1 macrophages produce high levels of proinflammatory and immunostimulatory cytokines, including interleukin 12 (IL-12), interleukin 23 (IL-23), tumor necrosis factor alpha (TNFα) etc., leading to tumor suppression." (PMID 34575569, 2021). "Further, excessive secretion of NO and cytokines like TNF-α by M1 macrophages also activate the immune system, promoting inflammatory responses and generating anti-tumor immunity." (PMID 34440860, 2021). "We expanded upon this strategy by specifically targeting attenuated human TNF to the tumor microenvironment via a clinical stage anti-EDB antibody named L19." (PMID 34576184, 2021). "Interferon-γ (IFN-γ) and tumor necrosis factor (TNF) were strictly required for tumor control in this model." (PMID 33141285, 2021). "IL-2 treatment combined with anti-CD3 therapy was found to restrict tumor cell proliferation and enhance secretion of TNF-α." (PMID 33669271, 2021). "M1 macrophages are regarded as mediators of resistance against tumor growth: they produce inflammatory cytokines, such as IL-1β and TNF-∝, which promote Th1 responses." (PMID 34037806, 2021). "MSCs are originally silent but become aggressive after receiving activation signals from tumor-derived pro-inflammatory cytokines, such as TNFα and IL1β, and/or ligation of the TLRs, such as TLR2, TLR3, and TLR4, that are expressed on MSCs." (PMID 33535613, 2021). "The tumor vasculature-homing properties of the CNGRCG-TNF fusion protein (called NGR-TNF) allows the targeted delivery of extremely low, yet pharmacologically active doses of TNF to tumor blood vessels, thereby avoiding systemic toxicity." (PMID 34063335, 2021). "In PAAD tissues, tumor-infiltrated immature M0 macrophages exhibit antitumor activity by secreting TNF-α." (PMID 34630563, 2021). "In comparison to MC-38 or LLC tumor cells, B16-F10 cells only minimally increased in cell death in response to Smac mimetics and exogenous TNF stimulation." (PMID 33546280, 2021). "While IFN-γ is the main regulator of PD-L1 expression in tumor cells, PD-L1 expression in TAMs seems to be regulated via TNFα." (PMID 34445397, 2021). "Because of stronger biological effects on tumor-killing activity and immunoinflammatory mediation, TNFα has received considerable amounts of attention." (PMID 33441130, 2021).
tumor (continued). "More importantly, we found that TAMCs-derived TNFα was a key mediator of the extensive apoptosis of tumour ECs." (PMID 34285232, 2021). "A recent study identified activation of the TNF/NF-κB cell survival pathway in tumor cells resistant to checkpoint blockade and CD8+ T cell–mediated killing, highlighting the central role of this pathway in immune escape by cancer cells." (PMID 34752416, 2021). "Of note, the high levels of ROS promote TAMs to generate TNF-α in the primary melanoma microenvironment, thus promoting tumor invasion and metastasis." (PMID 34405016, 2021). "In conclusion, the administration of TNFα-blocking agents emerges as a promising option in the oncology arena, but their combination with other therapies in specific tumor types needs to be further studied to attain optimal clinical results." (PMID 33540543, 2021). "TNF-α is a pleiotropic cytokine and a central mediator of inflammation, and chronic inflammation mediated by TNF-α is also associated with tumor progression." (PMID 34290231, 2021). "The effect of miR-1224-5p was further explored in TNF-α-treated human granulosa-like tumor (KGN) cells." (PMID 34637688, 2021). "The tumor-associated myeloid cells were activated by symbiotic intestinal bacteria via the TLR4 signaling to produce TNF and other inflammatory cytokines, which mediate the anti-tumor effects of these drugs." (PMID 34745119, 2021). "We then examined the changes in M2-like TAM markers (CD163, CD206, CD209, IL-10 and Arginase 1) and M1-like TAM markers (CD80, CD86, IL-12, and TNFα) induced by CM from ILT4-downregulated tumor cells." (PMID 33537094, 2021). "Increased secretion of IFN-γ and TNF-α by circulating T cells was observed, indicating improved systemic tumor specific T cell responses and there was improved immune cell infiltration in metastatic lesions." (PMID 33407605, 2021). "TNF-α is one of the most important cytokines that contributes to chronic inflammation and promotes the accumulation of Tregs in the tumor environment." (PMID 34576115, 2021). "Although TNF-α can induce tumor cell apoptosis, it has been abandoned as a cancer treatment due to systemic side effects." (PMID 34956913, 2021). "Whereas TNF production locally within the tumor microenvironment can promote tumor killing, TNF has also been shown to induce apoptosis in mature T cells and limit T cell trafficking into tumors." (PMID 34101617, 2021). "Under sufficient level, TNF-α has been also demonstrated to improve the efficacy of immunotherapy in tumors and initiate the apoptosis of tumor endothelial cells via the ligation of the TNFR1." (PMID 33924332, 2021). "In gastrointestinal cancer, lymphocytes secrete cytokines, such as interferon gamma (IFN-γ) and TNF-α, thereby controlling tumor growth and improving the prognosis." (PMID 34992504, 2021). "CXCL9 released by tumor cells can regulate the enrichment of NK cell subset that expresses tumor necrosis factor-related apoptosis-in-ducing ligand (TRAIL+NK cell) to tumor tissues." (PMID 33854600, 2021). "Lymphocytes regulate antitumor activity through host immune responses by inhibiting tumor proliferation and migration by secreting cytokines, such as TNF-α and INF-γ, and inducing cytotoxic apoptosis." (PMID 34244550, 2021). "The increased level of TNF-α induced an increase in blood influx to the tumor, thereby enhancing the colonization of Salmonella in tumor tissue." (PMID 34203478, 2021). "We found that the TNF-α secretion in tumor-infiltrating CD38− CD8+ T cells was significantly decreased when compare with CD38− CD8+ T cells in paired normal tissues, but not in tumor-infiltrating CD38+ CD8+ T cells." (PMID 33934206, 2021). "In summary, we described a novel, targeted TNF fusion protein that retains the potent in vivo anti-tumor activity of wild type TNF while reducing its systemic side effects." (PMID 34576184, 2021).
tumor (continued). "Tumor necrosis factor-alpha (TNF-α) and interleukin-1 beta (IL-1β) produced by inflamed immune cells such as tumor-associated macrophages (TAMs) promote the expression of inflammatory molecules in other cell types." (PMID 34084145, 2021). "Various approaches targeting the cytokine to the tumor, such as colloidal gold-bound TNF-α, gene transfer, recombinant TNF-α fused to an antibody anti-fibronectin of tumor endothelium (L19-TNF), failed to reach significant results in clinical trials." (PMID 34572013, 2021). "During interaction between tumor cells and ATC, several pro-inflammatory cytokines (IFNγ, TNF-α, IL-4, and IL-2) are released in the tumor microenvironment resulting in immunomodulation of the tumor cells, with upregulation of PD-L1expression on their surface." (PMID 34689789, 2021). "The Egf-1 promoter is activated by radiotherapy, which is usually applied in the tumor’s localized area; this helps regulate TNF-α’s transcription, keeping its activity restricted to a location and avoiding systemic toxicity." (PMID 33801589, 2021). "To further investigate the effects of VES on inflammatory factors in tumour-bearing mice, we examined TNF-α, IL-12, IFN-γ, IL-2 and IL-10 in the spleen by use of qRT-PCR assays." (PMID 34093795, 2021). "Upon validation, primary tumor tissues from the MFBD mice exhibited significant increases in TNFα expression compared to tumors from the OOBD fed mice as well as increased an expression of S1PR1 and MMP9; however, these were not statistically significant." (PMID 34371939, 2021). "IFN-γ and IL-2 promote the proliferation and differentiation of cytotoxic T lymphocytes and enhance the anti-tumor immune response, while TNF-α induces the apoptosis of target cells and contributes to the anti-tumor function." (PMID 35046962, 2021). "A compound containing the tumor vasculature-homing peptide Cys-Asn-Gly-Arg-Cys (NGR) has been fused to TNFα to create a tumor vasculature-homing version of TNF-α that avoids the toxicity of systemic TNFα administration (NGR-hTNF)." (PMID 34868953, 2021). "ELISA data showed that both IFNγ and TNFα were released from activated T cells in response to hEx3 treatment in a dose-dependent manner, although cell contact-dependent tumor cell killing is the major MOA of the TDB." (PMID 32666260, 2021). "Collectively, these data indicate that colibactin from E. coli promotes tumor development in a TNF-related manner." (PMID 33578830, 2021). "TNF-α was initially determined to be a natural immune serum mediator that can induce tumor hemorrhagic necrosis, it has a wide range of biological activities and can be used clinically as a target to immune diseases as well as tumors." (PMID 35069596, 2021). "While studies have shown the anti-tumor effects of TNF administration, endogenous production can also promote tumor cell survival through its activation of transcription factor NF-κB and is expressed by various cancer cells types." (PMID 33803078, 2021). "Inflammation often exists in the tumor microenvironment and is induced by inflammatory mediators such as TNF-α, IL-6, IL-1β." (PMID 33953676, 2021). "By targeting TNF signaling, metabolic protein 2-aminoethanethiol dioxygenase (Ado) was found to modulate sensitivity of tumor cells to TNF released by cytotoxic T cells." (PMID 34095145, 2021). "Despite of the CEA and PSA, other tumor markers including Tumor necrosis factor-alpha (TNF-α), carbohydrate antigen (CA199), and alpha-fetoprotein (AFP) were studied by the biosensing performed on either different material or shaped metasurfaces." (PMID 35009676, 2021). "Neutrophils can secrete various cytokines, such as granulocyte-macrophage colony-stimulating factor (GM-CSF), tumor necrosis factor-alpha (TNF-alpha), interleukin-1 (IL-1), and IL-8, to increase tumor formation, spread, and metastasis." (PMID 34532190, 2021).
tumor (continued). "FASN inhibition significantly suppresses the expressions of TNF-α, IL-6, IL-10, and ROS in TAMs, thereby impairing their pro-tumor activity." (PMID 34742349, 2021). "Another important finding in our experiment is that CD103+ CD3+ CD+ T cells secreted higher level of TNF-α to mediate an anti-tumor-immune response after stimulated by PD-1 blockade in vitro." (PMID 33934206, 2021). "The tumor necrosis factor delivery to tumor microenvironment antigens such as EDA, EDB, and fibroblast activation protein (FAP) demonstrated growth inhibition in multiple models." (PMID 33803078, 2021). "Tumor-associated macrophages (TAMs) also secrete IL-1β, which, together with the actions of TNF-α stimulate tumor angiogenesis by inducing the release of VEGF and CXCL8 by HNSCC cells." (PMID 35048046, 2021). "IL-6 is produced in response to local proinflammatory cytokines such as TNF-α, within the tumor microenvironment and can activate JAK/STAT3, MAPK, and PI3K/AKT pathways." (PMID 34912809, 2021). "The killing ability of Vγ2Vδ2 T cells induced by Y111 prompted us to check the production of killing cytokines, including IFNγ and TNFα, and cytotoxic mediator granzyme B in the co-culture of the T cell and tumor cells." (PMID 34040604, 2021). "TNF-α, IL-6, and IL-8 are particularly characteristic tumorigenic cytokines involved at the onset and all subsequent stages of tumor development, including promotion, progression, and metastasis." (PMID 34503198, 2021). "Activated astrocytes, in turn, produce IL-6, TNF-α, and IL-1β, which promote tumor cell proliferation." (PMID 33466236, 2021). "Pro-inflammatory cytokines (e.g. TNF-α, IL-6), particularly in chronic inflammation, can lead to reactive oxygen species-derived DNA-damage, resulting in tumor promotion." (PMID 33628623, 2021). "TNF can regulate immunity and enhance the anti-tumor cytolytic activity of NK cells and production of cytotoxicity-related proteins such as IFN-γ." (PMID 34307161, 2021). "Tumor-infiltrating monocytes and macrophages suppress the function of NK cells by repress interferons-γ (IFNγ), TNFα, and Ki-67 expression of NK cells through TGFβ1." (PMID 33406733, 2021). "In line with the observed changes in the heart and the liver, tumor-bearing mice had significantly increased renal expression of the pro-inflammatory cytokines IL-1α, IL-1β, TNF-α, and Mcp-1 compared to tumor-free mice." (PMID 34445729, 2021). "Targeting immune cells is important; indeed, the combination of a CD40 agonist and a PD-1 antagonist MAb exerts anti-tumor effects, which are manifested through tumor infiltration by IFNγ-, Granzyme B-, and TNFα-secreting effector T cells." (PMID 34439378, 2021). "Experiments in vivo have shown that GSDMC, along with nuclear PD‐L1 and caspase‐8, is required in the tumor necrosis induced by TNF‐α which are derived from macrophages." (PMID 34459122, 2021). "IFN-γ, TNF-α and IL-2 expression were relatively decreased in tumor-derived TRM cells compared with circulating T cells in melanoma patients." (PMID 34571883, 2021). "For example, MCs that secrete IL-1, IL-4, IL-6, and tumor necrosis factor (TNF)-α can actively eliminate tumor cells and halt tumorigenesis." (PMID 34829729, 2021). "On their turn, MHC-IIhigh (M1) TAMs and granulocytes can secrete, among others, TNFα, IL-1, and IL-12 to further ameliorate a Th1-polarized anti-tumor immune profile." (PMID 34445397, 2021). "A correlation of immune cell marker genes, including tumor-associated macrophages (TAMs) (CD209, CD206/MRC1, IL6, IL8, and CXCL10), MDSCs (CD33 and IL6), dendritic cells (DCs) (CD11c/ITGAX, CD209, TNF, and CD80) and Fusobacterium has been found in humans." (PMID 33823861, 2021). "Although TNF-α has the ability to induce tumor cell lysis, accumulating evidence shows that it plays critical roles in both tumor initiation and tumor development." (PMID 34948424, 2021).
tumor (continued). "Mast cells have been shown to promote dendritic cell migration to lymph nodes through TNF-α, histamine, and IL-6 and promote anti-tumor T-cell phenotypes through histamine." (PMID 34063789, 2021). "Our data indicate that EMT-high tumors lack CTL cytotoxic activity and hence tumor clearance due to limited support of IFNγ, TNFα, and IL2 and abundance of suppressive IL10 and TGFβ cytokines." (PMID 35096592, 2021). "An earlier study showed that CD137-CD137L (4-1BB-4-1BBL) interaction impairs NK cell anti-tumor activity in humans via induction of IL-10 and TNF release from AML cells, which allowed AML cells to evade being eliminated by NK cells." (PMID 34372571, 2021). "For example, when exposed to thymic stromal lymphoprotein from tumor or thymus, or TNF-α, DC express OX40 ligand, which is a member of the TNF superfamily (TNFSF4)." (PMID 33986746, 2021). "In contrast, the respective wild type TNF fusion protein showed lower tolerability when administered at an equimolar dose in the same tumor model." (PMID 34576184, 2021). "TNF-α is mainly produced by activated macrophages with a wide range of biological functions, including the induction of inflammation, anti-tumor effect, activation of T cells, and mediated immune response." (PMID 34026610, 2021). "In previous studies, elevated circulating levels of TNF-α were associated with advanced/metastatic NSCLC, tumor progression and poor survival, and our study data are consistent with this association." (PMID 34830880, 2021). "Several proinflammatory cytokines such as TNF-α, IFN-α/β, TGF-β and IL-4/6/17/27 have been shown to induce the expression of programed death ligand 1 (PD-L1) in tumor cells and tumor-associated stromal cells." (PMID 33806053, 2021). "This transcription is responsible for the secretion of interleukins including: IL-1b, IL-6, and IL-8; Tumor Necrosis Factors: TNF-a, TNF-b; inducible cyclooxygenase (COX-2 favor prostaglandin synthesis); and inducible nitric oxide synthase (iNOS)." (PMID 34682182, 2021). "The CYT-6091 nanodrug has achieved safety and targeted biologic response at the tumor site at a dose lower than that required for TNF-α alone." (PMID 34866165, 2021). "Increased immunosuppressive capacity was also due to TNF-induced reduction of the immune sensitivity of cancer in the IFNγ-rich tumor niche." (PMID 34068679, 2021). "While the classical IL-6 signaling pathway decreases the pro-inflammatory cytokines TNF-α and IL-1β, the trans-signaling pathway activates these pro-inflammatory pathways leading to chronical inflammation and tumor promotion." (PMID 34574641, 2021). "TNF-α is a highly pleiotypic cytokine, which is involved in a wide variety of processes that control inflammation and the anti-tumour response." (PMID 33808304, 2021). "In this process, the released inflammatory mediators (such as IL and TNF-α) damage the vascular endothelial cells, resulting in the hypercoagulable state of blood and making tumor cells adhere to the vascular wall." (PMID 34712737, 2021). "Different works have shown that in vitro stimulation of tumor cell lines by soluble factors such as IL-1β, TNFα, IL-6 or TGFβ can enhance c-Met expression." (PMID 34771724, 2021). "VPA/HPTA treatment alone significantly promoted an increase in the cell population expressing M1 marker (CD86; P <0.01) and M1 function markers (IL-12, IL-6, MHC-II, IFN-γ and TNF-α; P <0.01) at the transcriptional level in the tumor." (PMID 34054811, 2021). "One way to achieve this is through the expression of TNF from an oncolytic virus that is restricted to tumor sites, such as MYXV." (PMID 34553039, 2021). "These polarized macrophages prevent tumor growth by generating factors such as reactive oxygen and nitrogen species, or other secreted factors like TNFα, that lead to tumor cell death." (PMID 34025653, 2021).